PDX1 (pancreatic and duodenal homeobox 1)
Diseases named in the same sentence as PDX1 in open-access papers (continued):
Sharing a sentence is not in itself a finding about the gene and the disease.
diabetes (continued). "In addition, inactivation of the PDX1 gene has been observed in islets of individuals with T2D, suggesting that dysregulation of PDX1 is implicated in beta cell dysfunction in human diabetes." (PMID 38844555, 2024). "Likewise, Hnf1b, Gata4/Gata6, Pdx1 or Mnx1-deficient mice fail to develop pancreas of normal size and rather develop diabetes." (PMID 39322760, 2024). "HNF4G and PDX1 may induce PDAC-associated diabetes, whereas ABO may induce the causative effect of VTE on PDAC." (PMID 39002386, 2024). "In humans, mutations of Pdx1 are strongly associated with diabetes." (PMID 36574297, 2023). "This research uncovers a novel combination of SLC12A3 and PDX1 gene mutations in a Gitelman Syndrome patient, revealing intricate genetic factors that potentially disrupt glucose metabolism and shedding light on familial diabetes links." (PMID 38333726, 2023). "Up to date, only few mutations in the PDX1 gene have been linked to monogenic diabetes." (PMID 38162681, 2023). "This suggested the patient may be in the early stages of diabetes, with mild functional abnormalities due to mutations at the corresponding site of PDX-1." (PMID 38333726, 2023). "Determining the specific binding modes of PDX1 and its various interacting partners may provide insight into the effects of specific diabetes-associated mutations and PTMs." (PMID 36272648, 2022). "In addition, the runaway signal system of the small Ran GTPase significantly downregulates PDX-1 expression in postnatal mice, resulting in insulin deficiency, decreased cell proliferation rate, and diabetes." (PMID 36551213, 2022). "PDX1, another gene associated with both T2D and monogenic diabetes of the young (MODY), is thought to control β-cell function by regulation of mitophagy, a key mechanism for mitochondrial turnover and quality control, through controlling of the T1D-associated gene CLEC16A." (PMID 36276935, 2022). "In fact, a lot of diabetes phenotypes are associated with mutations in the PDX1 gene." (PMID 36589234, 2022). "This MLKL mutation may act as a modifier to the P33T PDX1 mutation, and points to a potential role of impairment of necroptosis in diabetes." (PMID 33795639, 2021). "A reduced expression of PDX1 may result in the pathogenesis of diabetes, which is a known risk factor of pancreatic cancer." (PMID 32456644, 2020). "High expression of Pdx1 stimulates endocrine cell differentiation, while decreased expression of Pdx1 or pancreas transcription factor 1 (Ptf1a) causes diabetes, a diseases related to impaired islet cells." (PMID 31921841, 2019). "It was found that the expression of NeuroD1-βcellulin reversed diabetes and maintained normoglycaemia, with associated up-regulation of both upstream and downstream β-cell transcription factors, including Pdx1, Pax6, Pax4, Nkx2.2, and Nkx6.1, as seen in the current study." (PMID 27070593, 2016). "In addition, impaired expression of pdx-1 as a consequence of hyperglycemia or increased lipid concentrations was thus associated with diabetes." (PMID 25695047, 2015). "A rare frameshift variant of PDX1 was previously found to associated with type 2 diabetes mellitus." (PMID 25813534, 2015). "Consequently, targeted disruption of PDX-1 gene in beta cells leads to beta-cell dysfunction and overt diabetes in mice, whereas mutations in PDX-1 have been linked to pancreatic agenesis and diabetes in humans." (PMID 25628604, 2014). "For example, Ex4 ameliorates the symptoms of diabetes and has been reported as capable of causing pancreatic precursor cell differentiation into islet cells and as activator of endogenous PDX1 in rats." (PMID 24963634, 2014). "STZ treatment also suppressed expression of a wide range of genes linked with key β-cell functions or diabetes development, such as G6pc2, Slc2a2 (Glut2), Slc30a8, Neurod1, Ucn3, Gad1, Isl1, Foxa2, Vdr, Pdx1, Fkbp1b and Abcc8, suggesting global β-cell defects in STZ-treated islets." (PMID 23828045, 2013).
diabetes (continued). "Gene mutations in human pdx-1 lead to the development of diabetes." (PMID 24705209, 2013). "Furthermore, tissue-specific Perk ablation in the entire pancreas (pcPKO, using Pdx1-Cre) causes both diabetes and exocrine atrophy; by contrast, mice with gene deletion only in islets (enPKO, using Ngn3-Cre) exhibit diabetes without exocrine atrophy." (PMID 17727724, 2007). "miR-204 upregulation, reduced NOX, RAGE, MMPs expression, downregulation of IKKβ/NF-κB phosphorylation, Nrf2, AdipoR1/2, JNK activation, TNF-α and IL-6, reduced macrophage infiltration, and ERK and PDX1 activation may reduce diabetes-associated CVDs and diabetic nephropathy." (PMID 37108833, 2023). "Thus, the overexpression of Srebf1 and Srebf2 has been shown to cause beta cell dysfunction and eventually diabetes, which at the cellular level is reflected by the repression of Pdx1 expression, impaired insulin secretion and content, as well as cellular triglyceride and cholesterol accumulation." (PMID 36232358, 2022). "Therefore, it is important to note the PDX1 variants in pregnant women with diabetes which may predispose these subjects and play a role during gestation and clinical outcomes." (PMID 28095440, 2017). "On the other hand, a significant increase in PDX1 was observed in the insulin-treated group as compared to the diabetes-untreated group." (PMID 40536613, 2025). "A reduced PDX-1 expression in T2DM compared with that in non-diabetes because of DNA methylation from hyperglycemia impairs the islet response to insulin sensitivity and exacerbates glucose metabolism." (PMID 41189666, 2025). "Induction of diabetes in both males and females significantly decreased Pdx1 gene expression and increased Pgc1α gene expression compared to NDC groups (P<0.0001)." (PMID 40809178, 2025). "Existing studies indicate that the decreasing of PDX1 expression leads to abnormalities in blood glucose regulation, thereby impacting the onset and progression of diabetes." (PMID 40405977, 2025). "Recent comparative genomic analyses revealed conserved and species-specific variants in key diabetes-associated genes, such as INS, PDX1, and GLUT4, across humans, dogs, and cats." (PMID 41012437, 2025). "In the context of diabetes,MALAT1 has been linked to beta-cell dysfunction via inhibitionof pancreatic and duodenal homeobox 1 (PDX-1)expression, which leads to reduced H3 histone acetylation." (PMID 41123190, 2025). "In this study, diabetes induction by alloxan resulted in considerable (P<0.05) suppression of Pdx-1 expression and DNA binding capabilities, which subsequently impaired the expression of insulin genes (Ins-1 and Ins-2)." (PMID 38234664, 2024). "It has been shown that the loss of MafA is an early indicator of β-cell inactivity due to hyperglycaemia, which precedes the reduction in PDX-1 and NeuroD1 for the development of diabetes." (PMID 38745946, 2024). "We used our pdx1 mutant zebrafish to test Gck modulation with cellular readouts in a whole organism diabetes model." (PMID 39580550, 2024). "Critical regulators of metabolism and pancreatic function, such as pancreatic and duodenal homeobox 1 (PDX1) and peroxisome proliferator-activated receptor gamma coactivator 1α (PGC-1α), are linked to diabetes." (PMID 39273309, 2024). "Previous studies have shown that PDX-1 and NeuroD1 are affected in genotypic animal models of diabetes, and there is also an increase in glucagon and alpha cells in pancreatic islets." (PMID 38745946, 2024). "Damage to pancreatic β-cell induced by oxidative stress or glucotoxicity lowers Pdx-1 expression, subsequently inhibits insulin production, and promotes diabetes development." (PMID 38234664, 2024). "ATF5 is a downstream target gene of pancreatic and duodenal homeobox 1 (Pdx1), which is a key pathogenetic factor of diabetes." (PMID 37095454, 2023). "The findings of HIPK2-mediated IPF1/PDX1 regulation highlight the key role of HIPK2 in glucose homeostasis in patients with diabetes." (PMID 37345014, 2023).
diabetes (continued). "Diabetes disturbed general parameters of β-cell mass (islet size, β-cell abundance and distribution) and health (insulin and PDX-1 expression), increased lipid peroxidation in islet cells, and phagocytic removal of iron-containing material." (PMID 37600723, 2023). "The important role of IPF/PDX1 in diabetes has been shown in a mice model in which targeted disruption of the IPF1/PDX1 gene leads to overt diabetes with decreased insulin expression and secretion." (PMID 37345014, 2023). "Replacing both endogenous alleles of Cdk4 with Cdk4-R24C prevented diabetes in IRS2-null male mice by rescuing β cell mass, function, and differentiation and restoring cytoplasmic FOXO1 location and nuclear PDX1 abundance in β cells in vivo." (PMID 37712417, 2023). "In summary, we report the discovery that CDK4 promotes insulin signaling and FOXO1 degradation in the pancreatic β cell, derepressing Pdx1 expression and rescuing diabetes in Irs2–/– mice." (PMID 37712417, 2023). "Expression of Pdx1 with a significant difference cf. ND rats in acini on the 60th day of diabetes and in duct epithelium—on the 30th day (Figure 3c1–c3)." (PMID 35457103, 2022). "In two previous studies, Pdx1 and a subset of other major islet-enriched transcription factors were found to be significantly decreased in human diabetes mellitus type 2 (T2DM) islet β-cells." (PMID 35697707, 2022). "In particular, several heritable mutations in PDX1 exons have been identified by genetic testing of MODY4 and neonatal diabetes patients." (PMID 36272648, 2022). "Similar studies in MODY and neonatal diabetes patients revealed amino acid substitutions within the DBD that are predicted to impair PDX1 target gene activation in development and in mature β cells via decreased DNA binding." (PMID 36272648, 2022). "Genome sequencing of the islets of T2D donors has revealed that the PDX1 gene is heavily methylated in diabetes." (PMID 36589234, 2022). "Previous studies have shown that Pdx1 plays a major role in diabetes and that reducing the expression of Pdx1 exacerbates diabetes." (PMID 35697707, 2022). "To conclude, published data indicate that alteration in redox-balance leads to dysregulated PDX1 levels and activity, which can result in diabetes." (PMID 36187092, 2022). "The development of drugs that target the relevant signaling pathway of PDX-1 in insulin regulation is crucial for diabetes treatment." (PMID 36551213, 2022). "A better understanding of PDX-1 will deepen our knowledge of the pathophysiology of DM and provide a scientific basis for exploring PDX-1 as a potential target for treating diabetes." (PMID 36551213, 2022). "Sequencing of large populations has indeed identified some rare variants (e.g. in MTNR1B, PPARG, SLC30A8, HNF1A, PDX1, PAM) that confer risk of type 2 diabetes that is intermediate between common SNPs and mutations causing monogenic diabetes." (PMID 35618782, 2022). "The development of drugs targeting the relevant signaling pathway of PDX-1 in insulin regulation will play a key role in treating diabetes; however, most related studies are animal experiments in the exploratory stage." (PMID 36551213, 2022). "Studies demonstrated that epigenetic changes of the Pdx1 gene, including both increased DNA methylation and histone modifications, can result in reduced Pdx1 expression and diabetes in postnatal life." (PMID 35457103, 2022). "Based on the importance of PDX-1 in pancreatic development and the maintenance of β cells, more research has begun to explore the application of PDX-1 in treating diabetes." (PMID 36551213, 2022). "The homeodomain transcription factor of pancreas/duodenum homeobox protein 1 (Pdx1) and human diabetes genes partially regulate beta cell survival via direct regulation of the activating transcription factor ATF5." (PMID 36187475, 2022). "At the early stage of diabetes, the expression of Pdx1 in acinar cells is still quite high, which allows to transdifferentiate them in IPCs." (PMID 35457103, 2022).
diabetes (continued). "Five participants presented other monogenic diabetes mutations (HNF1B: n = 2; PDX1: n = 2; APPL1: n = 1) but were excluded from the analysis." (PMID 35822264, 2022). "Genes implicated in monogenic diabetes include several encoding transcription factors involved in pancreatic beta cell development (e.g. HNF1A, HNF1B, HNF4A, PDX1, GATA4, GATA6)." (PMID 35618782, 2022). "This property of PDX1 makes it a particularly important target for gene or replacement therapy approaches to the treatment of diabetes." (PMID 36589234, 2022). "This review shows the unique position of PDX1 as a potential target in the genetic and cellular treatment of diabetes." (PMID 36589234, 2022). "Defective expression of Pdx1 has been documented in diabetes and this is attributed to oxidative stress." (PMID 36187092, 2022). "Reduced Pdx1 expression in the beta cell occurs in cellular models of glucose toxicity and accompanies the development of diabetes, correlating low Pdx1 levels with beta cell metabolic failure." (PMID 34115756, 2021). "In mRNA expression levels in isolated islets, insulin and its transcriptional factors such as Pdx-1 and MafA were significantly increased in combination therapy in an early phase of diabetes." (PMID 34373487, 2021). "PDX-1 is a transcription factor that plays a central role in β-cell function and its disruption develops diabetes with impaired expression of insulin and Glut2." (PMID 34960104, 2021). "Simultaneously, it reversed diabetes-associated oxidative stress by activating AMPK-Akt to inhibit FOXO1 and recovering PDX-1 nuclear localization." (PMID 34335803, 2021). "Knockout mice for MafA develop glucose intolerance and diabetes, lower expression of the insulin gene, PDX-1, NeuroD and GLUT2." (PMID 34638652, 2021). "In adult mice, impaired PDX1 expression coincided with changes in beta-cell number and insulin secretion and led to the development of diabetes within 14 days." (PMID 32708678, 2020). "We think that such new findings suggest that the downregulation of PDX-1 expression found in diabetes undermines insulin biosynthesis and secretion which explains, at least in part, the mechanism for β-cell glucose toxicity." (PMID 33322512, 2020). "The pdx1 mutant zebrafish most resembles human neonatal diabetes, as the early onset diabetic state occurs only in homozygous mutants and is associated with exocrine pancreas developmental defects." (PMID 32106290, 2020). "To confirm that NF-κB pathway repression and the subsequent elevation of β-cell stress cooperates with Pdx1 haploinsufficiency in diabetes development, we generated an independent mouse model." (PMID 31682591, 2020). "Herein, to induce the diabetes mellitus model at a specific time point, we generated Pdx1-dependent Mafb-deletion mice under Mafa knockout condition (A0BΔpanc), via tamoxifen-inducible Cre-loxP system." (PMID 32764399, 2020). "Pdx1 mutant zebrafish are a vertebrate genetic model that stably displays key features of human diabetes." (PMID 32106290, 2020). "Forkhead box (Fox)a2 and PDX1 are key regulators of β-cell development and function, and their mutations are associated with susceptibility to MODY, pancreatic hypoplasia and diabetes." (PMID 31322178, 2019). "It should further be noticed that genes of importance for islet function and diabetes such as PDX1, TCF7L2, FOXA2, FOXO1, NEUROD1 and BACH2 have C1, C3 or both these sites at their ATAC-seq open chromatin regions." (PMID 31123324, 2019). "It has been found for the neonatal diabetes genes GCK and PDX1, that homozygous mutations are a cause of neonatal diabetes and heterozygote mutations results in the monogenic form of diabetes called maturity onset diabetes of the young (MODY)." (PMID 31415576, 2019). "In this context, BL001-treated and immunized mice that develop diabetes retained islets with a significant number of PDX1+ cells and reduced insulitis at 8 weeks as compared to immunized mice." (PMID 29662071, 2018).
diabetes (continued). "Pdx1-Cre; EedKO mice presented with a range of glycemic control from normoglycemic to moderate diabetes already at 12 weeks of age." (PMID 29754954, 2018). "We excluded the remaining MODY genes (CEL, PDX1, PAX4, BLK, KLF11, NEUROD1) from this analysis since either very few missense mutations in these genes have been associated with early onset diabetes or the genetic evidence for association is limited." (PMID 29207974, 2017). "MG is a major precursor of advanced glycation end products, which were well known for their diabetes-inducing activities through impairment of an insulin transcription factor, pancreatic and duodenal homeobox-1 (PDX-1)." (PMID 28928902, 2017). "We identified MODY4 PDX1 variants in two subjects, MG19 with overt diabetes and MG101 with pre-gestational diabetes." (PMID 28095440, 2017). "Simultaneously, diabetes associated oxidative stress also activated FOXO1 and triggered nuclear exclusion of PDX1 which resulted in β-cell dysfunction." (PMID 29093682, 2017). "Impaired PDX1 location in the nucleus has been suggested as a mechanism of β-cell failure in diabetes." (PMID 29093682, 2017). "In human type 2 diabetes mellitus (T2D), PDX1 expression levels of islet beta cells are also compromised." (PMID 29096722, 2017). "Previous studies from our laboratory and others have shown that heterozygous Pdx1+/− mice develop diabetes due to decreased β-cell mass." (PMID 27137932, 2016). "Diabetes develops in Pdx1-haploinsufficient mice due to an increase in β-cell death leading to reduced β-cell mass and decreased insulin secretion." (PMID 27137932, 2016). "As Pdx1-dnBmpr1a and insulin promoter-derived Bmpr1a-deleted mice develop diabetes at 2–3 months of age, we also performed intraperitoneal glucose challenge in our pBmpr1aKO mice at 3 months of age." (PMID 26187948, 2015). "In this work we demonstrate that the pdx1 mutant zebrafish is a new vertebrate model of diabetes, as fish show the key features of decreased beta cells and insulin, and persistently elevated glucose levels." (PMID 26384018, 2015). "Since reduction of PDX1 is commonly seen in T2DM62, analyses of beta cell dynamics in the pdx1-mutant diabetes model that we describe can provide mechanistic insights that are applicable to more common forms of diabetes." (PMID 26384018, 2015). "The hyperglycemia responds to pharmacologic anti-diabetic treatment and, as often seen in mammalian diabetes models, beta cells of pdx1 mutants show sensitivity to nutrient overload." (PMID 26384018, 2015). "Overall, the homozygous phenotype of pdx1 mutant zebrafish resembles human neonatal diabetes in its early disease manifestation and severe endocrine dysfunction." (PMID 26384018, 2015). "Experiments in pre-clinical models of diabetes mellitus to assess in situ a Pdx1-mediated pancreatic islet differentiation of hBTSCs are needed." (PMID 26252949, 2015). "Transgenic mice with β-cell–targeted overexpression of HIF-1 by deletion of the Vhl gene exhibited reduced expression of Pdx1, Mafa, and Slc2a2 genes when they developed diabetes." (PMID 25503986, 2014). "It has recently been shown that under diabetes-related stress, the expression and activity of key β cell transcription factors, including MafA, Nkx6.1, and Pdx1, are compromised." (PMID 25233132, 2014). "Regarding the potential for long-term consequences of such gene expression alterations in fetal life, fetal growth restriction (FGR) in rodents permanently reduces PDX1 in β-cells via altered gene methylation, culminating in adult diabetes." (PMID 23457541, 2013). "NOD mouse islets, however, showed a down-regulation in the Pdx1 gene as the mice progressed toward overt diabetes." (PMID 23437231, 2013). "PDX-1 knockout is lethal in mice and mutation of PDX-1 leads to mature onset of diabetes of the young (MODY subtype IV) in mice and human patients." (PMID 22905092, 2012).